FOXM1 (forkhead box M1)
Diseases named in the same sentence as FOXM1 in open-access papers (continued):
Sharing a sentence is not in itself a finding about the gene and the disease.
cancer (continued). "Forkhead box protein M1 (FOXM1), an oncogenic transcription factor, plays a pivotal role in cancer pathogenesis by orchestrating metabolic reprogramming and stemness signaling, thereby contributing to therapeutic resistance." (PMID 41501006, 2026). "This silencing resulted in the suppression of key prostate cancer subtype 1 (PCS1) genes, specifically FOXM1 and RRM2, ultimately contributing to an aggressive phenotype." (PMID 39972491, 2025). "Plk1 and its downstream targets, including mitotic spindle positioning (MISP), RhoGDI1, and FoxM1, regulate proliferative and invasive capabilities through epithelial-mesenchymal transition (EMT) transition in cancer cells." (PMID 40166466, 2025). "For example, FOXM1, prominently enriched in CS2, modulates several cancer cell attributes, including proliferation, metastasis, and relapse." (PMID 40703658, 2025). "Post-transcriptionally, several miRNAs can regulate FOXM1 by binding to its 3’ UTR, a mechanism observed in many cancers." (PMID 40612352, 2025). "Kruskal–Wallis test was employed to compare the protein expression differences of UBE2S, HIF‐1α, and FOXM1 in the adjacent tissues, HIN, LIN, and cancer tissues." (PMID 41427004, 2025). "Recent studies indicate that downstream genes of the DREAM complex, such as FOXM1, PLK1, and AURKA, are critical for cancer cell proliferation across various cancers." (PMID 39796178, 2025). "Both FOXM1 and SPARC, almost undetectable in normal liver tissues, facilitate cancer cell migration and invasion in CRC." (PMID 40806530, 2025). "After validating FOXM1 KD at protein levels, we immunoblotted for phospho-ERK (p-ERK) levels which is a crucial regulator of cell growth, invasion, and cancer metastasis." (PMID 40630538, 2025). "CLDN1, EphB4, LAT1, FOXM1, HSP105α, ROBO1, and SPARC were identified as potential targets for common cancer antigens for primary CRC." (PMID 40806530, 2025). "Thiostrepton, another FOXM1-targeting agent, inhibits the expression of FOXM1 and its downstream effectors CCNB1 and CDC25B, ultimately inducing cancer cell death." (PMID 40746724, 2025). "Forkhead box protein M1 (FOXM1), a crucial transcriptional activator of LDHA and GLUT1, has potential effects on the glycolysis process in cancer." (PMID 39993964, 2025). "Of note, the CDK4/6 inhibitor palbociclib, which is clinically used in adjuvant cancer therapy, reduced the expression of E2F1, MYBL2, and FOXM1 and of endoreduplications." (PMID 40319068, 2025). "Further analysis of cancer-related genes showed that TPA and mezerein exposure upregulates several oncogenes, including Hmga1, Foxm1, Igf2bp2, Anln, Ezh2, and Suz12." (PMID 40182023, 2025). "For example, Regucalcin can promote the dormancy of cancer cells by inducing p38 MAPK activation and forkhead box M1 (FOXM1) inhibition." (PMID 38362620, 2024). "There is clearly a great need to define combination treatments most effective against the drug-resistant cancer cell state, and we have found that promoting ferroptosis by using activators of ferroptosis may be a good way to treat cancer and enhance therapeutic response to FOXM1 inhibition." (PMID 38980505, 2024). "FOXM1 binds largely to the proximal promoter regions of PLK4 and VEGF of the different cancer cell lines analyzed (ECC1, MCF-7, and SK-N-SH)." (PMID 38338955, 2024). "USP21 is known to deubiquitinate and stabilize several transcription factors such as YY1, FOXM1, EZH2, Nanog, and GATA3, promoting cancer cell proliferation, migration, and invasion and in vivo tumor growth." (PMID 39305962, 2024). "We evaluated the correlation between FOXM1 and GAPDH across pan-cancer samples in the TCGA database using a Pearson correlation method with a coefficient threshold of 0.3 and a p-value threshold of 0.05." (PMID 39062464, 2024).
cancer (continued). "We expected that STL001, being a more effective FOXM1 inhibitor as compared to its parental compound STL427944, should sensitize solid tumors-derived cancer cell lines more efficiently to current chemotherapies." (PMID 38697979, 2024). "Mounting evidence supports a multifunctional role for FOXM1 in HGSOC, including the promotion of cell proliferation, cell invasion, metastasis, chemotherapy resistance, cancer stemness, genomic instability, and altered metabolism." (PMID 38704607, 2024). "In various cancer cells, STL427944 was efficiently blocking FOXM1 activity, providing a completely new mode of action; however, due to some metabolic liabilities, it worked at concentrations that are considered too high for a targeted inhibitor." (PMID 38697979, 2024). "miR-320a directly targets SRY-Box Transcription Factor 4 (SOX4) and Forkhead Box M1 (FOXM1) and exerts a cancer-suppressive effect on CRC." (PMID 38315263, 2024). "For instance, the forkhead box protein M1 (FOXM1) is a transcription factor involved in the regulation of various cellular functions, including DNA damage response, cancer stem cells, and cell cycle regulation." (PMID 39273409, 2024). "The results indicated a significant positive correlation between FOXM1 and GAPDH expression in the majority of cancers." (PMID 39062464, 2024). "AKT pathway regulation of DDR is well studied and FOXM1 has been indicated to regulate the transcription of multiple DDR proteins and is crucial in cancer development and chemoresistance." (PMID 39560206, 2024). "Functional studies have shown its role in suppressing malignancy through its involvement in several pathways in cancer, where it mediates the regulation of critical genes, such as CDK4 and FOXM1." (PMID 39769441, 2024). "When Rb forms a complex with FOXM1, it represses GATA3 and PTEN, leading to the accumulation of poorly differentiated, cancer stem-like, and pro-metastatic cells." (PMID 39594778, 2024). "Through UALCAN analysis, high expression of FOXM1 or MET was related to shorter overall survival of UVM patients and higher cancer stages of UVM." (PMID 38342795, 2024). "FOXM1 is a cancer-promoting transcription factor that plays a critical role in TNBC and other highly aggressive cancers by driving cell proliferation, invasion, metastasis, and drug resistance." (PMID 39594778, 2024). "FoxM1, a putative EMT regulator and a determinant between mitogenic and invasive phenotypes of cancer, affects migration of macrophages and activation of lung fibroblasts in the local TME." (PMID 37968723, 2023). "Subsequently, we analyzed the correlation between FOXM1 and MRPL13 across various cancers and created a correlation map." (PMID 37827692, 2023). "A growing pool of evidence indicates that FOXM1 plays a key role in promoting and maintaining CSC populations in multiple cancers." (PMID 37174744, 2023). "Further analysis of the biological effects of their high correlation in cancers suggested that cell cycle was the most significant related pathway commonly regulated by HMGA1 and FOXM1." (PMID 37240870, 2023). "FOXM1 and FOXK1 have critical oncogenic roles in cancer through their antagonism of apoptotic signals and their promotion of cell proliferation, metastasis, angiogenesis, and therapeutic resistance." (PMID 37174744, 2023). "And USP5 could regulate the stability of many tumorigenesis‐associated proteins, such as forkhead box M1 (FoxM1), MAF bZIP transcription factor (c‐Maf), Tu translation elongation factor, mitochondrial, and snail family transcriptional repressor 2 (SNAI2) to promote the cancer progression." (PMID 37492786, 2023).
cancer (continued). "While only a small proportion of these BRCA1-like tumour harboured BRCA1 germline mutation, the finding that FOXM1 and downstream factors CDK4/6 are highly expressed in BRCA1-like tumours may have predictive implications in the setting of available CDK4/6-based therapies in BRCA1/2mut cancers." (PMID 36831687, 2023). "Consistently, this study showed that FoxM1 inhibition by siRNA led to the accumulation of ESCC cells at the G2/M phase, during which cancer cells are most sensitive to radiation." (PMID 36860922, 2023). "FOXM1 belongs to the FOX family of transcription factors but, in contrast to FOXO, it plays a pro-oncogenic role in cancer." (PMID 37894854, 2023). "Representative immunostaining from cancer sample sections confirmed that the levels of KI-67, a cell proliferation marker, and CDC25B, the FOXM1 downstream target gene, were dramatically down-regulated." (PMID 37344857, 2023). "Thus, new approaches to inhibiting FOXM1 and its activities, and combination therapies utilizing FOXM1 inhibitors in conjunction with known cancer drugs that work together synergistically, could improve cancer treatment outcomes." (PMID 37370117, 2023). "Investigation of FOXM1 in human cancers has expanded its known functions to include the promotion of proliferation, EMT, invasion, angiogenesis, and cancer stem cell (CSC) phenotypes." (PMID 37174744, 2023). "To date, a lot of APC substrates involved in cell cycle regulation have been demonstrated to be overexpressed in several cancer types, including CDC20, the Aurora A and B kinases (AURKA and AURKB, respectively) and Forkhead box M1 (FOXM1)." (PMID 37447165, 2023). "Previously, few miRNAs have been identified that regulate cancer cell proliferation, EMT, invasion, metastasis, apoptosis and drug resistance through their interaction with FOXM1." (PMID 37025658, 2023). "CDK 4/6 cyclin D complexes can also phosphorylate and regulate the expression of transcription factors, including FoxM1, Myc, and ME50, promoting an environment for cancer progression." (PMID 37845675, 2023). "Using the TCGA dataset, HMGA1 expression was identified to have a positive correlation with FOXM1, especially in LUAD, LIHC and PAAD, suggesting their common importance in cancer." (PMID 37240870, 2023). "Overexpression of FOXM1, FOXC2 and FOXP1 have been shown to be important in tumor development, drug resistance, metastasis and poor prognosis in a variety of cancer types." (PMID 37401400, 2023). "Only a small subset of these genes was differentially expressed in multiple carcinomas, including genes involved in cell cycle progression such as CCNB1, CCNE1, CCNE2, and FOXM1." (PMID 37345032, 2023). "This study suggests that the crosstalk between FOXM1 and BUB1B plays an essential role in the growth and survival of cancer cells." (PMID 35847923, 2022). "High FOXM1 expression has been reported to be an indicator of worse prognosis in UBC and other cancers and our findings suggest the potential for FOXM1 inhibition therapies." (PMID 35655252, 2022). "Previous studies have demonstrated that small molecule inhibitors of FoxM1 that block DNA binding, including FDI-6, thiostrepton, and sinomycin A, promote cancer cell death by apoptosis and by inducing cell cycle arrest." (PMID 35884976, 2022). "For example, FOXM1 promotes cyclin A2, B1, D1 and VEGF transcription to modulate the cell‐cycle progression and angiogenic ability of cancer cells." (PMID 35313071, 2022). "Therefore, the PI3K/Akt/FOXO3a axis may provide the link between CAFs and FOXM1 in cancer cell." (PMID 36401232, 2022).
cancer (continued). "Our results indicate that biologically targeted degradation of FOXM1 is an attractive therapeutic strategy, and antagonist peptide-containing FOXM1-PROTACs as both degrader and inhibitor of FOXM1 could be developed as a safe and promising drug for FOXM1-overexpressed cancer therapy." (PMID 36171633, 2022). "A DNA aptamer targeting FOXM1 DBD suppresses its transcriptional activity and inhibits cancer cell proliferation." (PMID 35680842, 2022). "FOXM1, a member of the Forkhead transcription factors family, which is regulated by FOXO transcription factors, has a role in tumorigenesis and cancer progression." (PMID 35346234, 2022). "ALKBH5 regulates FOXM1, G6PD, SOX2, and AKT2 expression in an m6A-dependent manner to promote cancer cell proliferation, invasion and drug resistance." (PMID 35945641, 2022). "FOXM1 belonging to the conserved forkhead box (FOX) transcription factor family, significantly contributes to cancer development and progression." (PMID 36435510, 2022). "In CRC, the MCF2LAS1/miR-874-3p/FOXM1 axis and MCF2LAS1/miR-874-3p/CCNE1 axis can promote cancer cell apoptosis, inhibit cancer cell proliferation, invasion, migration and EMT process." (PMID 35465322, 2022). "To this end we utilized the publicly available transcriptomic expression datasets from healthy and cancer testis samples and compared the correlation between NANOS3, PUM1, FOXM1, and the model cell cycle targets." (PMID 35743036, 2022). "The knockdown of FOXM1 downregulated the CD44 and SOX2 CSC markers, which are involved in the emergence of CSCs in various types of cancers." (PMID 35887129, 2022). "Furthermore, the overexpression of FOXM1 leads to the acquisition of an EMT phenotype by activating the mesenchymal cell markers ZEB1, ZEB2, Snail2, E-cadherin, and vimentin, which are associated with increased spheroid-forming capacity and cancer stem cell surface markers (CD44 and EpCAM)." (PMID 36613925, 2022). "A precedent for such negative regulation of FOXM1 by KLF4 can be found in gastric and pancreatic cancer." (PMID 35852857, 2022). "It has been highlighted that an enhanced population of cancer stem cells (CSCs) contributes to chemoresistance and recurrence, and that ALKBH5 promoted CSC property through increasing FOXM1 and NANOG." (PMID 35628623, 2022). "Several cancer-related TFs such as JUNB, JUND, Forkhead box protein M1 (FOXM1), and ETS1 were part of the TF–mRNA regulatory network." (PMID 36232337, 2022). "Exosomal miR-620 secreted by ESCC cells inhibited the aerobic glycolysis via FOXM1/HER2 axis and promoted cancer metastasis." (PMID 35651785, 2022). "Experiments have recently confirmed FOXM1's cell cycle regulation of LMNB1 and, thus, provide a mechanistic basis for a gene-gene scaling relationship between FOXM1 and LMNB1 across many cancers in TCGA." (PMID 35719698, 2022). "Further we found that CSFs in each developing organ, as well as the corresponding cancer, were likely regulated by FOX (FOXM1), MYC, and BRD family of transcriptional regulators." (PMID 36509773, 2022). "ALKBH5 promotes cancer progression by regulating TIMP3, FOXM1, CDKN1A, JAK2, FOXM1, AURKB, G6PD, HBx, USP1, NANOG, PVT1, IGF1R lncRNA NEAT1, and lncRNA RMRP expression." (PMID 35945641, 2022). "Here, we report that the transcription factor FOXM1 activates PDK1, a glycolysis gatekeeper, and promotes glycolysis, leading to cancer progression and poor prognosis in NPC." (PMID 35656815, 2022). "On the other hand, the TAT used in our FOXM1-PROTAC has successfully improved the permeability of FIP-1 peptide and facilitated FOXM1-PROTAC enter cancer cells to degrade FOXM1." (PMID 36171633, 2022).
cancer (continued). "In this study, we used public database and tissue microarrays to analyze the expression pattern of FoxM1 and STMN1 and found a strong positive correlation between FoxM1 and STMN1 in multiple types of cancer." (PMID 33526768, 2021). "We then tested the expression pattern of FoxM1 and STMN1 in 18 cancer cell lines derived from LIHC, GC and CRC, and found a significantly positive correlation between FoxM1 and STMN1 in tumor cells." (PMID 33526768, 2021). "We show that FOXM1 and RHNO1 are tightly co-expressed in both normal and cancer cells and tissues, including individual cells, and that their co-expression is controlled by a bidirectional promoter (F/R-BDP)." (PMID 33890574, 2021). "This, along with conservation of the F/R-BDP in vertebrates, suggests that FOXM1 and RHNO1 function cooperatively in normal physiology and cancer." (PMID 33890574, 2021). "And then using two independent short hairpin RNAs (shRNAs), we knocked down endogenous FoxM1 and STMN1, respectively, in three different types of cancer cell lines." (PMID 33526768, 2021). "The FOXM1 transcriptional network includes pluripotency genes, such as SOX2, NANOG, and OCT4, in several cancer models." (PMID 34205406, 2021). "To investigate the expression pattern of FoxM1 and STMN1 in different types of cancers, we first analyzed the mRNA levels of FoxM1 and STMN1 in the Oncomine database." (PMID 33526768, 2021). "In agreement, after normalization to the canonical cell proliferation marker MKI67, the FOXM1/RHNO1 expression ratio was similar in normal and cancer tissues." (PMID 33890574, 2021). "Collectively, the novel autophagy-dependent mode of FOXM1 suppression by STL427944 validates a unique pathway to overcome tumor chemoresistance and improve the efficacy of treatment with conventional cancer drugs." (PMID 34262016, 2021). "Further experiments are necessary to dissect the relationship between the overexpression of FOXM1 and the TME in cancer progression." (PMID 33804240, 2021). "As both FOXM1 and E2F1 are master transcription factors in human cancer, inhibition of MNK1/2-dependent expression of FOXM1 and E2F1 will have a broad impact on transcriptome." (PMID 33564073, 2021). "FOXM1 and MYBL2 were significantly higher in tumors than in adjacent normal tissues in 70% (23/33) of cancers." (PMID 34489925, 2021). "Hnf4a expression resulted in a decreased expression of cancer-promoting factors LSD1, SETD1A, PRMT1, FOXM1, FAK, and SNAI1, and also an increased expression of CDH1." (PMID 34595169, 2021). "Based on our finding that STMN1 is transcriptionally regulated by FoxM1, we wondered to know the biological function of STMN1 in cancer cells." (PMID 33526768, 2021). "We found that FDI-6 and FOXM1 shRNA impaired Olaparib-induced expression of CDK1, CCNA1, CCNB1, and CDC25B to inhibit the mitosis of cancer cells." (PMID 34880209, 2021). "The results showed a significantly positive correlation between FoxM1 and STMN1 in all cancer samples derived from the TCGA database." (PMID 33526768, 2021). "Although the broader role of USP28 in regulating other targets in cancers remains to be determined, identification of USP28 as a FOXM1 deubiquitinase will hopefully lead to additional studies focused on USP28 as a therapeutic target in PC." (PMID 34584067, 2021). "To address this question, we compared FOXM1 and RHNO1 expression in Genotype-Tissue Expression (GTEx) normal tissues vs. TCGA pan-cancer tissues using the Toil method." (PMID 33890574, 2021).